VIM (vimentin)
Diseases named in the same sentence as VIM in open-access papers (continued):
Sharing a sentence is not in itself a finding about the gene and the disease.
Obesity (20 papers, 2017 to 2026). Accumulation of substantial excess body fat. "The obesity-exacerbated TNBC progression was attenuated after IF, which decreased cyclin B1 and vimentin levels and reduced the proinflammatory signature in the obesity-associated tumor microenvironment." (PMID 38999849, 2024). "Kim and colleagues studied the effects of vimentin deficiency, providing us with the interesting finding that it prevents obesity and insulin resistance in mice fed an HFD." (PMID 35454311, 2022). "We observed increased GFAP and VIMENTIN immunoreactivity in multiple different congenital knockout mouse models of BBS prior to the development of obesity, suggesting that loss of BBSome function causes reactive astrocytes." (PMID 31072410, 2019). "In addition, it has been pointed out that VIM deficiency prevents high-fat diet-induced obesity." (PMID 38703299, 2024). "Adipocyte CM enhanced the wound closure assay and cell invasion by increasing EMT-related protein levels, such as vimentin, snail, and twist, indicating an obesity-induced EMT change." (PMID 38999849, 2024). "Dectin-1 activation induced by vimentin promoted obesity and insulin resistance in a diet-induced obesity mouse model." (PMID 37606991, 2023). "Recently, a study on vimentin-null mice with high-fat diet-induced obesity showed less weight gain, less adiposity, improved glucose tolerance and lower fasting glucose, as well as higher levels of triglycerides and free fatty acids." (PMID 37189422, 2023). "Fungal microbiota was undetectable by our ITS sequencing analysis, further validating the role of Dectin-1 and vimentin in obesity-driven inflammation and impaired glucose homeostasis." (PMID 28614714, 2017). "Thus, vimentin, like CK-18, seems to be a promising marker for predicting obesity and liver disease, although its significance requires further research." (PMID 37189422, 2023). "The proteomic analysis of the obesity-induced mouse liver revealed that a high-fat diet changed the expression of intermediate microfilament cytoskeleton proteins, in particular up-regulating CK-18, CK-8 and vimentin." (PMID 37189422, 2023). "Other studies support the hypothesis that the intermediate filament protein vimentin is involved in obesity and type 2 diabetes, by participating not only in GLUT4 vesicle trafficking but also in lipolysis through an interaction with hormone-sensitive lipase." (PMID 37189422, 2023). "Thus, the study shows that obesity promotes hepatic DNL in the insulin-resistant state via Vimentin, a hitherto unknown organokine." (PMID 42320628, 2026). "Likewise, obesity is a factor that correlates with a trend for increased Vimentin expression." (PMID 40523922, 2025). "On the other hand, IF targets the obesity-induced parameters, lowering body weight and blood glucose/cholesterol to destroy the obesity-associated microenvironment of TNBC with downregulated cyclin B1/vimentin and Mφ accumulation followed by decelerated TNBC progression and mortality (green arrows)." (PMID 38999849, 2024). "Increased vimentin levels may be due to the AT hypoxia in our HFD-induced obesity models." (PMID 28614714, 2017). "Therefore, vimentin may in part drive the HFD-induced obesity by directly binding to and activating Dectin-1." (PMID 28614714, 2017). "Vimentin knockout mice (vim-/-) were fed a HFD for 10 weeks, and a number of obesity outcomes were measured." (PMID 39057066, 2024). "Our proteomics analysis showed a positive interaction between ANXA and vimentin in the AT of the WT and MyD88 KO DIO mice, suggesting that vimentin is increased during obesity due to low oxygen availability in the AT." (PMID 28614714, 2017). "A comparison of vimentin protein levels in lysates from tumor tissues between HFD and HFD-IF groups revealed that IF diminished obesity-induced vimentin expression, but PCNA protein levels were no different in these two groups." (PMID 38999849, 2024).
Obesity (continued). "Differential gene expression revealed that genes associated with innate immune responses (LYZ), antigen processing and presentation (HLA-DRB1, HLA-DRB5, IFI30), as well as cell signaling and migration (VIM, RGS1, NCF) were upregulated in the HBC subset with pregravid obesity." (PMID 39872537, 2024). "Furthering our understanding of the roles of vimentin and its involvement in disease mechanisms could help develop the IF as a possible biomarker for MASLD and obesity and help identify possible solutions." (PMID 39057066, 2024). "The reverse-phase protein microarray revealed that vimentin expression was significantly increased in mammary epithelial cells of obese women compared to those of non-obese women, appearing as an obesity-sensitive EMT protein." (PMID 38999849, 2024). "IFI16, ERBB2, VIM (vimentin) and CAV1 are crucial factors for advancement of obesity." (PMID 36837510, 2023). "The mechanism of action of vimentin was mediated by the expression of CD36 and the glucose transporter GLUT4 on the cell membrane of adipocytes, linking intermediate filaments and intracellular trafficking with obesity and insulin resistance." (PMID 37189422, 2023). "The effect of the secretome of CAAT isolated from patients with obesity and BC was investigated on the mRNA expression levels of CSC markers, such as CD24 and CD44 as well as EMT markers, such as vimentin and E-cadherin, was investigated in MDA-231 and SUM-149 cells using qRT-PCR." (PMID 35927653, 2022). "Our results have suggested that T2D complicated with metabolic syndrome, such as dyslipidaemia and obesity, could induce EMT with a reduction in the expression of E−cadherin and an increase in the expression of vimentin through RAGE activation in PSCs." (PMID 34769147, 2021). "Although hepatocytes do not typically express vimentin, adipocytes do, and therefore, vimentin could be involved in mechanosensitive processes that affect the interplay between these two key cell types in MASLD and obesity." (PMID 39057066, 2024).
ovarian tumor (20 papers, 1994 to 2025). "Interestingly, another study found that low vimentin expression in stroma and high vimentin expression in cancer cells was associated with prolonged overall survival (OS) in patients with ovarian tumours." (PMID 39780187, 2025). "Overexpression of vimentin may be associated with increased metastatic capacity through the epithelial to mesenchymal transformation (EMT) of ovarian tumor cells." (PMID 34770931, 2021). "Western blot analysis of primary ovarian tumors revealed that miR-675 expression led to the upregulation of epithelial markers cytokeratin-7 and E-cadherin, while mesenchymal markers N-cadherin, Vimentin, and Snail2 were downregulated." (PMID 39744561, 2025). "In metastatic tumour deposits in omentum, VIM protein expression appeared higher than in primary ovarian tumours, likely due to small tumour deposits and a high proportion of VIM-positive stromal cells and adipocytes." (PMID 39682273, 2024). "There are limited studies, however, exploring the relationship between vimentin expression and ovarian tumor prognosis." (PMID 34770931, 2021). "The top row represented the strong binding of V3M2, V5M2 and anti-vimentin antibodies in human ovarian tumor tissue, while the bottom panel represented the weak binding of V3M2, V5M2 and anti-vimentin antibody in normal human ovarian tissue." (PMID 34770931, 2021). "In the current case, the epithelial cells of the ovarian tumors were also positive for alpha-inhibin, vimentin, and CD99." (PMID 33019452, 2020). "E-cadherin, N-cadherin, cytokeratin 19 and vimentin mRNA expression levels in human ovarian tumor-primary cultures." (PMID 28934230, 2017). "Contrary to that, the expression of VIM decreased in different stages and grades of ovarian tumours compared to normal ovaries, compared to IHC data in our in-house samples, which showed an increasing trend in different stages and grades of tumours compared to benign ovaries." (PMID 39682273, 2024). "Meanwhile, the results of immunohistochemistry confirmed that shRAN or shHSBP1 caused the down-regulation of Vimentin, N-cadherin, and promoted the expression of E-cadherin, indicating that the knockdown of RAN and HSBP1 inhibited the invasive ability of ovarian tumor in vivo." (PMID 32398961, 2020). "In addition, we also performed immunostaining on primary ovary tumor sections using survivin, vimentin, and cytokeratin-7." (PMID 30241553, 2018). "Additionally, NCe-FA also reduced the expression of the EMT marker, vimentin, indicating its ability to maybe limit ovarian tumor metastasis." (PMID 26979107, 2016). "Ovarian tumors in mice treated with the SLN-STAT3 ODN-decoy had reduced potential for invasion due to the downregulation of VEGF, MMP9, CDH2, and Vimentin (VIM) and elevated levels of CDH1." (PMID 38067351, 2023). "In summary, we have identified two specific truncated aptamer motifs (V3M2 and V5M2) with successful binding to the extracellular matrix protein vimentin of IGROV cells and human ovarian tumor tissue." (PMID 34770931, 2021). "The aim of this study was to apply the antibodies for marker of EMT vimentin and markers of pluripotency NANOG, SOX2 and SSEA-4 to ovarian tumor sections of women with epithelial cancer, and focus on morphological changes in the ovarian surface epithelium." (PMID 28231820, 2017). "Therefore, we used the ovarian tumor samples to assess the binding of V3M2 and V5M2 to vimentin expression ovarian tumors." (PMID 34770931, 2021). "Ovarian tumor sections were immunostained with EIF5A2, vimentin, and cytokeratin-7 antibodies." (PMID 33827661, 2021). "However, the 4 other markers ESR, PGR, Vimentin, and HER2 had no value for discrimination, with a possible reason being that they are all associated with transcription and tumorigenesis in ovary tumors." (PMID 37335673, 2023).
sarcomatoid carcinoma (20 papers, 2009 to 2026). A malignant epithelial neoplasm characterized by the presence of spindle cells and anaplastic morphologic features. "The second, based on the “sarcomatous” component's expression of cytokeratins (particularly high molecular weight cytokeratin) which is often associated with the expression of mesenchymal antigens like vimentin, focuses on the carcinomatous nature of the proliferation—sarcomatoid carcinoma." (PMID 28050299, 2016). "Sarcomatoid carcinomas demonstrated epithelial to mesenchymal transition as the cells displayed reduced CK8 expression (with occasional foci of CK8 loss) coupled with nearly ubiquitous vimentin co-expression." (PMID 22022528, 2011). "Re-biopsy of a mediastinal lymph node demonstrated sarcomatoid carcinoma positive for vimentin and pan-cytokeratin AE1/AE3." (PMID 42309826, 2026). "The results revealed the presence of spindle cell carcinoma (SpCC) with vimentin and cytokeratin positivity." (PMID 38500938, 2024). "We also detected positive staining for vimentin, a mesenchymal marker, in prostatic sarcomatoid tumor cells in the compound mice, suggesting the that these sarcomatoid carcinomas are undergoing the EMT process." (PMID 30677079, 2019). "To include LCNEC, we expanded our antibody panel not only with vimentin, which can serve as a marker for sarcomatoid carcinoma, but also with neurendocrine markers (CD56, Synaptophysin, Chromogranin A)." (PMID 23418554, 2013). "Microscopic examination showed sheets of pleomorphic spindled to epitheliod cells staining positive for cytokeritin and vimentin, indicative of sarcomatoid carcinoma." (PMID 27785184, 2012). "It showed co-expression of Vimentin, CK7, D2–40, focal PanCK, but it stained negatively for EMA, CEA, EpCAM, usually positive in sarcomatoid carcinoma." (PMID 28810922, 2017). "In Case 2, the tumor cells exhibited positive staining for CK and Vimentin, negative staining for SMARCA4, and the patient was positive for SMARCA4-deficient sarcomatoid carcinoma." (PMID 41170461, 2025). "Most sarcomatoid carcinomas exhibit EMA positivity in both epithelial and mesenchymal-like components and approximately 90% of small bowel sarcomatoid carcinomas are positive for vimentin." (PMID 39777335, 2024). "Sarcomatoid carcinoma typically shows positive immunoreactivity for cytokeratin and vimentin and negative immunoreactivity for S100 and CD34." (PMID 39211661, 2024). "Another report demonstrated that PSCN and sarcomatoid carcinoma stained positive for vimentin, and that some PSCNs stained positive for CK and EMA, which may lead to misdiagnosis of sarcomatoid carcinomas." (PMID 24765166, 2014). "Sarcomatoid carcinoma cells were partially positive for AE1/AE3 and strongly positive for vimentin, whereas all the tumor cells were negative for neuroendocrine markers and other mesenchymal markers, such as desmin, SMA, myglobin, mygenin, S-100, DOG-1, CD34, CD117, CD15, CD30, and CD20." (PMID 33761637, 2021).
esophageal squamous cell carcinoma (19 papers, 2011 to 2025). Esophageal squamous cell carcinoma (ESCC) is a type of esophageal carcinoma (EC) that can affect any part of the esophagus, but is usually located in the upper or middle third. "Furthermore, miR-146a inhibits vimentin expression, suppressing cell proliferation, migration, and invasion in esophageal squamous cell carcinoma, potentially linked to advanced stages and poor overall survival." (PMID 37371575, 2023). "On the contrary, the relatively high copy number of mtDNA was associated with low protein expression of E-cadherin and high expression of Vimentin in TE1 esophageal squamous cell carcinoma (ESCC) cells." (PMID 35454769, 2022). "CircGOT1, whose expression is upregulated in esophageal squamous cell cancers, is able to promote downstream GOT1 expression through direct binding to miR-606, which ultimately affects E-cadherin, N-cadherin, and Vimentin expression for cellular EMT." (PMID 40109856, 2025). "miR-301a targets the tumor-promoting factor WNT1 to increase the radiosensitivity of esophageal squamous cell carcinoma (ESCC) cells, while suppressing drug resistance and EMT by targeting Snail and Vimentin." (PMID 35805066, 2022). "In esophageal squamous cell cancer, tumors displaying high budding showed weak membranous E-cadherin and strong cytoplasmic vimentin immunostaining, while tumors exhibiting low budding showed strong membranous localization of E-cadherin and no cytoplasmic vimentin." (PMID 27136592, 2016). "In esophageal squamous cell carcinoma (ESCC) cell lines, TWIST1 is a crucial transcription factor that enhances the epithelial-mesenchymal transition (EMT) by downregulating E-cadherin and upregulating mesenchymal genes such as N-cadherin, ZEB2, vimentin, and fibronectin." (PMID 38589525, 2024).
invasive breast carcinoma (19 papers, 2010 to 2026). A carcinoma that infiltrates the breast parenchyma. "It was further supported by several studies reporting, among others, co-expression of both E-cadherin and vimentin in, e.g., invasive breast cancer, that when exhibited by the tumors concomitantly conferred the worst DFS and OS outcomes." (PMID 36613607, 2022). "Taken together, these findings suggest Vimentin as a potential biomarker and therapeutic target of breast invasive carcinoma and other aggressive cancers." (PMID 33530981, 2021). "It has been observed that in some of the patients vimentin, has been expressed in the ductal component of the invasive breast cancer tissues." (PMID 26906973, 2016). "Vimentin expression in invasive breast carcinomas is generally considered to indicate the epithelial-to-mesenchymal transition or myoepithelial histogenesis." (PMID 25267010, 2014). "Immunohistochemical stains for CK5/6, CK14, EGFR and vimentin were performed on 500 invasive breast carcinomas." (PMID 23082819, 2012). "Its marked expression in poorly differentiated tumors suggests that vimentin may serve as a useful adjunct prognostic marker of aggressive tumor biology in invasive breast carcinoma." (PMID 42220707, 2026). "Taken together, we observed decreased expression of epithelial markers (E-cadherin and Desmoplakin) and found increased expression of mesenchymal markers (N-cadherin, Zeb1, Snail, Slug and Vimentin) along with an increased expression of hTERT in invasive breast cancers." (PMID 29907642, 2018). "In addition, hATT-CMs were also enriched in complement component 3 (C3) (20-fold change), involved in the activation of the complement system, and in vimentin and desmin (8.5-fold and 6.5 fold change), which are mesenchymal cell proteins related to an invasive breast cancer phenotype." (PMID 30123423, 2018). "The current study demonstrated quantitative differences in telocyte marker expression—specifically vimentin, CD10, CD34, and c-Kit—across molecular subtypes of invasive breast cancer." (PMID 40724542, 2025). "Based on this retrospective study, histological markers of 113 individuals sufferingfrom invasive breast cancer -such as estrogen receptor (ER), progesterone receptor,HER-2 receptor, E-cadherin, CK5/6, vimentin and Ki67 were examined byIHC technique." (PMID 31210439, 2019). "Immunohistochemical analysis allowed us to evaluate the expression of vimentin, ER, Ki67, CD44 and TGFβ with respect to the presence of BOLCs in breast-infiltrating carcinoma." (PMID 30327566, 2018). "Previous research has revealed that invasive breast carcinomas expressing vimentin have a higher rate of tubulin microtentacles after detachment than non-invasive cell lines that do not express vimentin." (PMID 37046635, 2023).